ANXA1 (annexin A1)
Diseases named in the same sentence as ANXA1 in open-access papers (continued):
Sharing a sentence is not in itself a finding about the gene and the disease.
Obesity (continued). "To investigate whether ANXA1 affected mice obesity via PPARγ in vivo, we treated HFD-fed Anxa1AKO mice with GW9662 (intraperitoneal injection every other day at a dose of 1 mg/kg for 16 weeks)." (PMID 39174522, 2024). "Furthermore, the potential roles of ANXA1 in adipocytes was investigated using an in vitro cell-based model mimicking the inflammatory status that is observed during obesity." (PMID 35684160, 2022). "Higher levels of cleaved ANXA1 are observed in obesity, which may mediate its anti-inflammatory and pro-resolving actions locally, thus, ANXA1 may have an important pathophysiological mechanism involved in the inflammatory status observed in obesity." (PMID 35684160, 2022). "The anti-inflammatory actions of ANXA1 may be compromised by obesity which may alter ANXA1’s autocrine, paracrine effects on adipose tissue to resolve inflammation." (PMID 35684160, 2022). "Further investigations are required to understand the role of plasma ANXA1 protein in obesity and determine whether it has a therapeutic role in obesity management." (PMID 35684160, 2022). "PPARG, ADAMTS5, TIMP4, ANXA1, AGTR1, and CXCL12 genes are evidently associated with obesity, suggesting that the influence of these genes on obesity may be similar to the influence of fat accumulation in hMSCs." (PMID 34899844, 2021). "Elevated expression of ANXA1 in adipose tissue of obese mice parallels the increased ANXA1 expression observed in adipose tissue of obese humans, but contrasts with the attenuated plasma levels of ANXA1 reported in human obesity." (PMID 24312665, 2013). "Because ob/ob mice develop obesity even when fed chow diet, use of these animals also allowed us to investigate whether upregulation of ANXA1 requires feeding a HFD." (PMID 24312665, 2013). "Therefore, the role and regulation of ANXA1 in the context of obesity and diabetes remain to be elucidated." (PMID 24312665, 2013). "A previous study reported on decreased ANXA1 levels in plasma of patients with obesity." (PMID 24130820, 2013). "To investigate whether obesity induced by HFD alters expression of ANXA1 in adipose tissue, we used male C57BL6 mice, a strain that is highly susceptible to DIO." (PMID 24312665, 2013). "Considering the increased relative cell count of inflammatory cells and preadipocytes with high expression of ANXA1 and the compensatory protective increase in ANXA1 levels in obesity, this may explain the higher ANXA1 levels in the SAT of mice and humans with obesity." (PMID 39174522, 2024). "Annexin A1 is known to have beneficial effects in islets by potentiating glucose‐stimulated insulin release and protecting against apoptosis, so its secretion from expanded adipose depots in obesity may lead to improved islet function via binding to the formylpeptide receptor FPR2." (PMID 36245259, 2022). "We found an increased expression of ANXA1 in skeletal muscle in GDM and increased levels of ANXA1 in serum has been reported in obesity-related type 2 diabetes mellitus." (PMID 34416903, 2021). "Significant induction of ANXA1 mRNA was observed in adipose tissue of both C57BL6 and Balb/c mice with high fat diet (HFD)-induced obesity versus mice on chow diet." (PMID 24312665, 2013). "This can further explain that the anti-obesity effect of ANXA1 is exerted intracellularly, not through extracellular receptors." (PMID 39174522, 2024). "While rodent obese models have shown no changes in ANXA1 concentrations our group has shown plasma ANXA1 to be reduced in people with obesity." (PMID 35684160, 2022). "The source of plasma ANXA1 protein or the reason for its attenuation in obesity is not currently understood." (PMID 35684160, 2022). "As ANXA1 is an essential regulator of BBB tightness through stabilisation of the cytoskeleton, we would speculate that its expression or post-translational modification might also be affected in obesity." (PMID 27655189, 2016).
Obesity (continued). "Notably, the elevation of ANXA1 in mice and humans with obesity does not seem to support the hypothesis that ANXA1 prevents obesity." (PMID 39174522, 2024). "Production of Annexin A1 (ANXA1), a protein that mediates the anti-inflammatory action of glucocorticoids, is altered in obesity, but its role in modulation of adiposity has not yet been investigated." (PMID 24312665, 2013).
COVID-19 (21 papers, 2021 to 2026). A disease caused by infection with severe acute respiratory syndrome coronavirus 2. "In patients with COVID-19, AnxA1 level was shown to be inversely associated with the degree of lung involvement." (PMID 36766501, 2023). "Clinically, elevated AnxA1 at presentation predicts an increased risk of thrombotic events in patients with COVID-19." (PMID 36556102, 2022). "In conclusion, we demonstrate that the pro-resolving mediator of inflammation, AnxA1, is increased in the sera of patients with moderate and severe COVID-19 and is associated with adverse clinical outcomes." (PMID 36556102, 2022). "Annexin A1 (ANXA1) is a proresolving protein regulated by glucocorticoids, the standard care for severe and critical COVID-19 patients." (PMID 42072630, 2026). "Bush and colleagues demonstrated increased AnxA1 plasma levels in moderate and severe COVID-19 patients accompanied by higher numbers of circulatory neutrophils." (PMID 40956847, 2025). "Different studies explored AnxA1 circulating levels or its mRNA expression in immune cells by using sc-RNA-seq in COVID-19 patients." (PMID 40956847, 2025). "Overall, these results demonstrate that MHV-3 infection in BALB/c mice replicates key features of COVID-19 and also leads to increased AnxA1 staining in critical areas of lung inflammation, suggesting an important role for AnxA1 in this context." (PMID 40956847, 2025). "In the lungs of COVID-19 patients, AnxA1/FPR1 pair interaction was shown to be enhanced during infection and crucial for the interplay between squamous epithelial cells and myeloid cells, such as neutrophils and macrophages." (PMID 40956847, 2025). "Specific drugs, including dexamethasone, hydrocortisone, and prednisolone, have been used to manage severe cases of COVID-19 that target ANXA1." (PMID 38238762, 2024). "Canacik and colleagues identified AnxA1 as a biomarker for the severity of COVID-19, as the levels of the protein in the serum of patients with the severe disease were decreased compared to those of healthy volunteers, or even patients with mild disease." (PMID 37190040, 2023). "Dysregulation of AnxA1 expression has been reported in patients with novel coronavirus disease 2019 (COVID-19)." (PMID 36766501, 2023). "One study previously reported decreased AnxA1 in patients with severe COVID-19 compared to moderate cases and controls." (PMID 36556102, 2022). "AnxA1 was significantly higher in the moderate and severe cases of COVID-19 compared to the healthy controls." (PMID 36556102, 2022). "Dexamethasone, an exogenous glucocorticoid upstream of AnxA1, has, in fact, been shown to alter type I interferon active neutrophils in COVID-19 and improve outcomes for patients with severe COVID-19." (PMID 36556102, 2022). "In this study, we demonstrated that AnxA1 is significantly increased at presentation and during hospital admission in patients with moderate and severe COVID-19." (PMID 36556102, 2022). "We longitudinally evaluated AnxA1′s role in terms of inflammation, vascular damage, and clinical outcomes in a large prospective cohort of patients with COVID-19." (PMID 36556102, 2022). "Overall, AnxA1 was assessed in 220 out of 228 (96%) patients with COVID-19; eight patients were excluded because of insufficient sampling." (PMID 36556102, 2022). "We studied the serum levels of AnxA1 at presentation and over time in a large and well-defined cohort of patients with COVID-19 to delineate AnxA1′s role in terms of inflammation, vascular damage, and clinical outcomes." (PMID 36556102, 2022). "The capacity to secrete higher levels of AnxA1 to buffer the pro-inflammatory state was eventually exceeded in patients with severe COVID-19." (PMID 36556102, 2022). "In this review, we summarize existing knowledge of annexin functions and potential therapeutic applications of annexin A1, A2 and A5 in sepsis and COVID-19." (PMID 34566657, 2021).
COVID-19 (continued). "In conclusion, ANXA1 may be involved in COVID-19 recovery processes, and its interplay with RvE1 may ameliorate hyperinflammation." (PMID 42072630, 2026). "However, Shenoy and co-workers showed a significant decrease in AnxA1 serum levels in severe COVID-19 patients." (PMID 40956847, 2025). "In addition, rising levels of systemic AnxA1 are correlated with the severity of disease and with high neutrophil counts during COVID-19." (PMID 40956847, 2025). "The expression of ANXA1 is markedly increased in the sera of critically ill COVID-19 patients." (PMID 38238762, 2024). "In line with the finding of Ural and co-workers, another recently published study demonstrated that AnxA1 levels are augmented during COVID-19, and may be related to increased ICU admission." (PMID 37190040, 2023). "Although it has been suggested that AnxA1 analogues may be helpful in COVID-19 patients, it is difficult to reconcile the findings of all studies evaluating the concentration of AnxA1 in COVID-19 patients." (PMID 37190040, 2023). "This is consistent with the results of a metabolomic analysis of severe COVID-19 patients, which found that AnxA1 plays an important role in infection with severe acute respiratory syndrome coronavirus (SARS-CoV-2)—the causative agent of COVID-19—and is a potential therapeutic target." (PMID 36766501, 2023). "A pre-print by Hoffmann and colleagues demonstrated that convalescent patients of COVID-19 have circulating monocytes that up-regulate the expression of AnxA1, suggesting that the levels of AnxA1 may be related to the convalescent state of the patients." (PMID 37190040, 2023). "Finally, multivariate logistic regression identified AGRG6, PICAL, CTRB1, and ANXA1 as independent factors that predicted response to MSC therapy in patients with severe COVID-19." (PMID 38072927, 2023). "However, another independent study from Ural and colleagues showed the opposite: the levels of AnxA1 in the serum of COVID-19 patients were increased compared to the control group." (PMID 37190040, 2023). "This may be because patients with low ANXA1 levels before treatment have weak interactions with complement molecules and lipids, mediating a low cytokine response in COVID-19." (PMID 38072927, 2023). "One may assume that deregulated homeostasis of AnxA1 can therefore play a role in the pathogenesis of severe COVID-19." (PMID 36556102, 2022). "Future studies should evaluate whether hyperinflammation in COVID-19 patients can be diminished by targeting FPR2 through the administration of human recombinant AnxA1 or Ac2-26 peptide." (PMID 36556102, 2022). "Elevated levels of AnxA1 may reflect the pro-inflammatory state of patients with moderate and severe COVID-19." (PMID 36556102, 2022). "These cell adhesion molecules (ANXA1 and ICMA2), cytokine binding and receptor activity genes (CD44, CD45, CD47, CD74, and THBS1), and inflammatory genes (FPR1 and SELL) have been reported to be associated with COVID-19." (PMID 35172892, 2022). "In addition to ANXA1, which has been used to treat severely ill COVID-19 patients, another novel drug target like CLEC3B was also identified." (PMID 33859163, 2021). "Therefore, AnxA1-based peptides or FPR2 agonists might hold great promise as therapeutic agents against COVID-19." (PMID 37190040, 2023). "Notably, AnxA1 tended to increase over time in patients admitted to the hospital with COVID-19." (PMID 36556102, 2022). "A case–control study demonstrated that Annexin A1 is a potential prognostic biomarker in the diagnosis of COVID-19 pneumonia and in predicting the need for ICU treatment in patients with COVID-19." (PMID 38072927, 2023). "At presentation, AnxA1 was significantly higher in the moderate (30.1 (IQR, 16.0–42.0) ng/mL; p < 0.0001) and severe cases of COVID-19 (28.9 (IQR, 17.3–53.6) ng/mL; p < 0.0001) compared to the healthy controls (14.9 (IQR, 10.4–22.4) ng/mL)." (PMID 36556102, 2022).
COVID-19 (continued). "Thus, also Annexin A1 could be a therapeutic avenue for COVID-19 to explore in future studies." (PMID 36591311, 2022). "Furthermore, a glucocorticoid dexamethasone treatment, in severe COVID-19 patients, is known to induce anti-inflammatory AnxA1 and also enhances its translocation to cell membrane, could reduce the membrane deposition of AnxA2, making it unavailable for the virus entry and replication." (PMID 34681689, 2021). "Our results showed that low levels of DDX55, ANXA1, PICAL, and AGRG6 before treatment, as well as elevated levels of CTRB1 pre-MSC treatment, were biomarkers for predicting response to MSC therapy in severe COVID-19 patients." (PMID 38072927, 2023). "scRNA-seq results of COVID-19 find that changes of host factors including EN-RAGE, TNFSF14, oncostatin M, ANXA1, FPR1, and S100A8/9 are correlated with disease severity, revealing the possible pathogenesis of severe COVID-19 and potential host therapeutic targets." (PMID 35495713, 2022). "Moreover, longitudinal data on the changes in AnxA1 levels during the course of COVID-19 are lacking." (PMID 36556102, 2022).
diabetes (21 papers, 2013 to 2025). "Further, Annexin A1 deficiency was associated with more severe STZ-induced diabetes accompanied with more severe nephropathy (indexed by albumin-to-creatinine ratio, glomerular area and fibrosis) and cardiomyopathy (indexed by ejection fraction, fractional shortening, etc.)." (PMID 34943928, 2021). "In other studies, AnxA1 deficiency worsened pathological remodelling of the mesenteric vasculature in insulin-resistant, but not insulin-deficient animals, suggesting that AnxA1-based therapies could provide benefits for reducing vascular injury in diabetes." (PMID 33810523, 2021). "AnxA1 has been shown to afford protection in murine diabetic nephropathy by decreasing p38, ERK and JNK, and activating Akt signaling, suggesting that AnxA1 could be a potential therapeutic strategy for treating renal dysfunction caused by diseases such as diabetes." (PMID 29659553, 2018). "Among these, Paraoxonase-1 (PON1), AMP deaminase-1 (AMPD1) and Annexin 1 (ANXA1) are involved in diabetes or GDM." (PMID 34416903, 2021). "With respect to diabetes mellitus, increased renal Annexin A1 is shown to correlate with kidney function and outcomes in established diabetic nephropathy in a human cohort." (PMID 34943928, 2021). "We will focus on the role of ANXA1 in diseases with a large inflammatory component focusing on diabetes and microvascular disease." (PMID 31114582, 2019). "Murine models of diabetes have demonstrated a similar rises in ANXA1 levels in serum as seen in humans with diabetes." (PMID 31114582, 2019). "The urinary ANXA1 was detectable as early as the stage of normoalbuminuria in diabetes patients with 52.94%, microalbuminuria with 72.73%, and macroalbuminuria with 100%." (PMID 24591769, 2014). "In this study, we demonstrated that ANXA1 protein was earlier present in 52.94% of diabetes patients with normoalbuminuria." (PMID 24591769, 2014). "Clarifying the interaction between the psEV conferred upregulation of ANXA1 and increases in insulin synthesis warrants further investigation and may hold promise for the development of therapies to treat diabetes." (PMID 39432712, 2024). "In addition, annexin A1 was a potential therapeutic target in diabetes and the treatment of microvascular disease such as DKD39,40." (PMID 37188670, 2023). "Finally, ANXA1 regulates glucose metabolism and is proposed to be involved in diabetes, as ANXA1 knockout mice suffer a diabetic phenotype." (PMID 34148071, 2021). "Finally, we will explore the possibility of exploiting ANXA1 as a novel therapeutic target in diabetes and the treatment of microvascular disease." (PMID 31114582, 2019). "As endogenous ANXA1 protected against the development experimental diabetes and treatment with hrAXNXA1 improved the diabetic phenotype of HFD-fed mice, we next investigated the potential mechanisms underlying the observed beneficial effects of both hrANXA1 and endogenous ANXA1." (PMID 30972066, 2019). "Numerous reports have demonstrated that protein expression of ANXA1 is decreased in diabetes." (PMID 31114582, 2019). "We use urine from diabetes patients, the most common single cause of ESRD in the world, to evaluate whether urinary ANXA1 could serve as an early biomarker for kidney injury." (PMID 24591769, 2014). "Moreover, the impact of ANXA1 in other age‐related diseases, such as neurodegenerative diseases and diabetes mellitus, indicates that ANXA1 might affect the aging process." (PMID 38358087, 2024). "Thus, Annexin A1 may represent a novel therapeutic option for microvascular complications of diabetes mellitus." (PMID 34943928, 2021). "Additionally, these overexpression models can be applied to further explore ANXA1’s potential as a therapeutic target for diabetes, and to determine whether β cells exposed to glucotoxicity can maintain sufficient insulin production in the presence of elevated ANXA1 levels." (PMID 39432712, 2024).
diabetes (continued). "This is consistent with human data, where individuals with diabetes exhibit lower circulating levels of LXA4 and annexin A1 when compared to healthy controls." (PMID 39563316, 2024). "However, the biological consequence of elevated ANXA1 in diabetes remains unclear." (PMID 31114582, 2019). "ANXA1 was expressed by 33.2% of pMSCs and was expressed constitutively among individuals with or without diabetes." (PMID 41422462, 2025). "It was concluded that Annexin A1 is a pivotal regulator of RhoA activity, restoring IRS-1 signaling, and that hrANXA1 may offer therapeutic benefit for complications of type 2 diabetes mellitus." (PMID 34943928, 2021). "Additionally, ANXA1 levels were not further elevated in patients who presented with diabetes and CKD." (PMID 30972066, 2019). "Although dysregulation of ANXA1 and ANXA2 has been documented in diabetes, changes in ANXA3 have not been reported." (PMID 37895816, 2023).